TARDBP (TAR DNA binding protein)
Diseases named in the same sentence as TARDBP in open-access papers (continued):
Sharing a sentence is not in itself a finding about the gene and the disease.
amyotrophic lateral sclerosis (continued). "Abnormal cytoplasmic mislocalization of transactive response DNA binding protein 43 (TARDBP or TDP-43) in degenerating neurons is a hallmark of amyotrophic lateral sclerosis (ALS) and frontotemporal lobar degeneration with ubiquitin-positive inclusions (FTLD-U)." (PMID 27928708, 2017). "This protein causes the phosphorylation of TAR DNA Binding Protein-43 (TDP-43), a phenomenon which is associated with the onset and progression of a neurodegenerative disorder, Amyotrophic Lateral Sclerosis (ALS)." (PMID 28155653, 2016). "TAR DNA-binding protein 43 (TDP-43) is a major component in aggregates of ubiquitinated proteins in amyotrophic lateral sclerosis (ALS) and frontotemporal lobar degeneration (FTLD)." (PMID 26444430, 2015). "The presence of lower molecular weight species comprising the C-terminal region of TAR DNA-binding protein 43 (TDP-43) is a characteristic of TDP-43 proteinopathy in amyotrophic lateral sclerosis (ALS) and frontotemporal lobar degeneration (FTLD)." (PMID 25788357, 2015). "Mutations in the copper/zinc superoxide dismutase (SOD1), TAR DNA-binding protein 43 (TDP-43), and FET family proteins are associated with the development of amyotrophic lateral sclerosis (ALS), a fatal neurodegenerative disease." (PMID 24804206, 2014). "TAR DNA-binding protein (TDP-43) was identified as the major ubiquitinated component deposited in the inclusion bodies in amyotrophic lateral sclerosis (ALS) and frontotemporal lobar degeneration with ubiquitin-positive inclusions (FTLD-U) in 2006." (PMID 25090004, 2014). "TAR-DNA binding protein (TDP-43) is an RNA-binding protein that has been suggested to play a major role in the pathogenesis of amyotrophic lateral sclerosis (ALS) and frontotemporal dementia (FTD)." (PMID 25329970, 2014). "A predominantly nuclear heterogeneous nuclear ribonucleoprotein (hnRNP) TAR DNA-binding protein-43 (TDP-43) is found as a major component of ubiquitinated inclusions in amyotrophic lateral sclerosis (ALS) and frontotemporal lobar dementia (FTLD-U)." (PMID 24948216, 2014). "TDP-43 (TAR DNA-binding protein) is the major pathological protein in amyotrophic lateral sclerosis (ALS) and frontotemporal lobar degeneration with ubiquitin-positive inclusions (FTLD-U)." (PMID 25090004, 2014). "Cytosolic aggregation of the nuclear RNA-binding protein TDP-43 is a histopathologic signature of degenerating neurons in amyotrophic lateral sclerosis (ALS), and mutations in the TARDBP gene encoding TDP-43 cause dominantly inherited forms of this condition." (PMID 23468938, 2013). "TAR DNA-binding protein 43 (TDP-43) is a protein that is involved in the pathology of Amyotrophic Lateral Sclerosis (ALS) and Frontotemporal Lobar Degeneration (FTLD)." (PMID 24252504, 2013). "Five to 10% of cases of amyotrophic lateral sclerosis are familial, with the most common genetic causes being mutations in the C9ORF72, SOD1, TARDBP and FUS genes." (PMID 23228179, 2013). "Phosphorylated and truncated TAR DNA-binding protein-43 (TDP-43) is a major component of ubiquitinated cytoplasmic inclusions in neuronal and glial cells of two TDP-43 proteinopathies, amyotrophic lateral sclerosis and frontotemporal lobar degeneration." (PMID 23840565, 2013). "TAR DNA binding protein (TDP-43), encoded by the TARDBP gene on human chromosome 1, is a major pathological component of the neuronal inclusions associated with amyotrophic lateral sclerosis (ALS) and frontotemporal lobar degeneration (FTLD-TDP)." (PMID 22539017, 2012). "In 2006, TAR-DNA binding protein 43 kDa (TDP-43) was discovered to be in the intracellular aggregates in the degenerating cells in amyotrophic lateral sclerosis (ALS) and frontotemporal lobar degeneration (FTLD), two fatal neurodegenerative diseases." (PMID 22697423, 2012). "The TAR-DNA-binding protein (TDP-43) has been postulated as the disease protein in amyotrophic lateral sclerosis and frontotemporal lobar dementia with ubiquitin-positive inclusions." (PMID 22482072, 2012).
amyotrophic lateral sclerosis (continued). "Mutations in the SOD1, TARDBP, and FUS genes have been commonly identified in Amyotrophic Lateral Sclerosis (ALS)." (PMID 21829392, 2011). "Regions of reduced local gyrification index showed spatial convergence with cortical expression of amyotrophic lateral sclerosis-related genes such as TARDBP and C9orf72, enriched for biological processes related to protein aggregation, axon guidance and synaptic signalling." (PMID 41523190, 2026). "TDP-43 is a nuclear protein encoded by the TARDBP gene, which forms pathological aggregates in various neurodegenerative diseases, collectively known as TDP-43 proteinopathies, including amyotrophic lateral sclerosis (ALS) and frontotemporal dementia (FTD)." (PMID 40906043, 2025). "Amyotrophic lateral sclerosis (ALS) is an incurable motor neuron disease characterised symptomatically by the progressive loss of motor function resulting from the deposition of aggregated proteins including TAR DNA-binding protein 43 (TDP-43) in motor neurons, spinal cord, and the motor cortex." (PMID 38252383, 2024). "Furthermore, mutations in TAR DNA-binding protein 43 (TDP-43), associated with amyotrophic lateral sclerosis (ALS), have been linked to cardiovascular issues, particularly cardiac dysfunction." (PMID 39334823, 2024). "Other amyotrophic lateral sclerosis–linked RBP and TAR DNA-binding protein 43 condensates are buffered by the addition of tRNA, whereas nuclear-enriched abundant transcript 1 lncRNA, which can form rG4, facilitates TAR DNA-binding protein 43 LLPS." (PMID 39510192, 2024). "Amyotrophic lateral sclerosis (ALS) is a degenerative condition affecting the motor neurones, characterized by a multifaceted genetic makeup—mutations in genes such as SOD1, C9orf72, TARDBP, and FUS cause ALS." (PMID 39759457, 2024). "C-terminally phosphorylated TAR DNA-binding protein of 43 kDa (TDP-43) marks the proteinaceous inclusions that characterize a number of age-related neurodegenerative diseases, including amyotrophic lateral sclerosis, frontotemporal lobar degeneration and Alzheimer's disease." (PMID 38585945, 2024). "Various MN diseases, such as spinal muscular atrophy and amyotrophic lateral sclerosis (ALS), are thought to be caused in part by dysfunction of RNA-binding proteins (RBPs) including fused in sarcoma (FUS) and TAR DNA–binding protein 43kDa (TDP-43)." (PMID 39226364, 2024). "The TAR DNA-binding protein 43 (TDP-43) is another example of a misfolded protein implicated in a number of neurodegenerative diseases, such as amyotrophic lateral sclerosis (ALS), frontotemporal dementia (FTD), and limbic-predominant age-associated TDP-43 encephalopathy (LATE)." (PMID 37627229, 2023). "Specific proteins, e.g., α-synuclein (α-syn) and clusterin in Parkinson ́s disease (PD); creatinine, human serum albumin (HSA), and TAR DNA binding protein 43 kDa (TDP-43) in amyotrophic lateral sclerosis (ALS); as well as RNAs’ biomarkers have been discovered in biofluids." (PMID 36614231, 2023). "It is well known that autophagy is a fundamental process to eliminate protein aggregations such as Aβ and tau in AD; α-synuclein (α-syn) in PD; huntingtin in Huntington’s disease (HD); or TAR DNA-binding protein 43 (TDP-43) in amyotrophic lateral sclerosis (ALS)." (PMID 35897658, 2022). "Cytoplasmic mislocalization and aggregation of TAR-DNA binding protein 43 (TDP-43) is found in the vast majority of patients with amyotrophic lateral sclerosis (ALS), and in approximately half of patients with frontotemporal dementia (FTD) with ubiquitin inclusions." (PMID 36294886, 2022). "TARDBP is known to be an RNA-binding protein related to neurodegenerative diseases such as frontal temporal lobe degeneration and amyotrophic lateral sclerosis and may play an important role in cell metabolism including glucose metabolism and lipid metabolism." (PMID 34830998, 2021).
amyotrophic lateral sclerosis (continued). "Intronic circRNAs can accumulate in the cytoplasm and bind to TAR DNA binding protein 43 (TDP43) and this could be a beneficial effect in the treatment of amyotrophic lateral sclerosis because it suppresses TDP43 toxicity." (PMID 34944400, 2021). "AEP has previously been reported to cleave aggregate-forming proteins, such as amyloid precursor protein (APP), microtubule associated protein tau (MAPT) and TAR-DNA binding protein 43 (TDP43) and is also implicated in an FTLD-related disorder, amyotrophic lateral sclerosis (ALS)." (PMID 34344440, 2021). "Cytoplasmic aggregated deposits of the nuclear TAR DNA-binding protein 43 (TDP-43) characterize neurons in most amyotrophic lateral sclerosis (ALS) and approximately half of frontotemporal lobar degeneration (FTLD) cases, now collectively called TDP-43 proteinopathies." (PMID 34452489, 2021). "Amyotrophic lateral sclerosis (ALS) is a neurodegenerative disease of the central nervous system (CNS) causing progressive loss of muscle control and often characterized by a cytotoxic accumulation of TAR DNA-binding protein 43 (TDP-43)." (PMID 34659260, 2021). "Nuclear depletion, abnormal modification, and cytoplasmic aggregation of TAR DNA-binding protein 43 (TDP-43) are linked to a group of fatal neurodegenerative diseases called TDP-43 proteinopathies, which include amyotrophic lateral sclerosis (ALS) and frontotemporal lobar degeneration (FTLD)." (PMID 34759799, 2021). "For example, alpha-synuclein in Parkinson’s disease; amyloid-beta (Aβ) and hyperphosphorylated tau (p-tau) in Alzheimer’s disease; mutant huntingtin proteins in Huntington’s disease, and mutant superoxide dismutase 1 (SOD1) and TAR DNA binding protein 43 (TDP-43) in amyotrophic lateral sclerosis." (PMID 34440645, 2021). "Genetic analyses of patients with amyotrophic lateral sclerosis (ALS) have revealed a strong association between mutations in genes encoding many RNA-binding proteins (RBPs), including TARDBP, FUS, hnRNPA1, hnRNPA2B1, MATR3, ATXN2, TAF15, TIA-1, and EWSR1, and disease onset/progression." (PMID 32547363, 2020). "Interestingly, both TARDBP and ATXN2 are implicated in neurological disorders such as amyotrophic lateral sclerosis (ALS); in addition, Ataxin-2 has been implicated in microRNA regulation." (PMID 33101370, 2020). "Amyotrophic Lateral Sclerosis (ALS) and Frontotemporal Dementia (FTD) share overlapping genetic causes and disease symptoms, and are linked neuropathologically by the RNA binding protein TDP-43 (TAR DNA binding protein-43 kDa)." (PMID 29142232, 2017). "The TAR DNA binding protein of 43 kDa (TDP-43) has been identified as a major component of the ubiquitinated aggregates in neurons of patients with either frontotemporal lobar degeneration (FTLD) or amyotrophic lateral sclerosis (ALS)." (PMID 28686708, 2017). "Here, we established a cell culture model to characterize the cell-to-cell transmission of TAR DNA-binding protein and α-synuclein, involved in amyotrophic lateral sclerosis and Parkinson’s disease, respectively, using the small nine amino acid influenza hemagglutinin tag." (PMID 28373710, 2017). "Amyotrophic lateral sclerosis (ALS) is a debilitating neurodegenerative condition that is characterized by progressive loss of motor neurons and the accumulation of aggregated TAR DNA Binding Protein-43 (TDP-43, gene: TARDBP)." (PMID 28476168, 2017). "IIS reduction was also reported to protect model nematodes from proteotoxicity of other neurodegeneration-linked, aggregative proteins including HD-associated polyQ stretches and the amyotrophic lateral sclerosis (ALS)-linked mutated protein, TAR DNA binding protein 43 (TDP-43)." (PMID 24261972, 2014). "CuII(atsm) could also modify TAR-DNA binding protein 43 (TDP-43) metabolism, a protein central to neuropathology of amyotrophic lateral sclerosis and a sub-set of frontotemporal dementia cases." (PMID 24587210, 2014).
amyotrophic lateral sclerosis (continued). "TAR DNA-binding protein 43 (TDP-43) is a protein constituent of pathologic cytoplasmic and intranuclear inclusions in neurons and glia of patients with sporadic and familial forms of amyotrophic lateral sclerosis (ALS) and frontotemporal lobar degeneration (FTLD)." (PMID 24312274, 2013). "TAR DNA‐binding protein 43 (TDP‐43) is the major pathological protein in amyotrophic lateral sclerosis (ALS)." (PMID 41563042, 2026). "Pathological TAR DNA-binding protein-43 (TDP-43) is a defining feature of several neurodegenerative diseases, including amyotrophic lateral sclerosis (ALS), frontotemporal dementia (FTD) and Alzheimer's disease (AD)." (PMID 41807703, 2026). "Examples include α-syn in PD, tau and amyloid beta (Aβ) in AD, TAR DNA-binding protein 43 in amyotrophic lateral sclerosis (ALS), Huntingtin protein in Huntington’s disease (HD), and transthyretin (TTR) in systemic amyloidosis." (PMID 40534869, 2025). "Amyotrophic lateral sclerosis (ALS) is a fatal neurodegenerative disease characterised by the presence of pathological forms of TAR DNA-binding protein 43 (TDP-43) in the brain and spinal cord in almost all cases (97%)." (PMID 40824324, 2025). "Amyotrophic lateral sclerosis (ALS), also known as motor neuron disease, is characterized by progressive degeneration of motor neurons and accumulation of TAR DNA-binding protein 43 (TDP-43) in the brain." (PMID 41002422, 2025). "A key pathological feature of Amyotrophic Lateral Sclerosis (ALS) and Frontotemporal Dementia (FTD) is the loss of nuclear localization and accumulation of cytoplasmic inclusions of TAR-DNA binding protein 43 (TDP-43)." (PMID 41460923, 2025). "For instance, in cellular models of TDP-43 (also known as TARDBP) proteinopathy, a feature of amyotrophic lateral sclerosis (ALS), glutamate-elicited Ca2+ responses were significantly lower than in control cells." (PMID 39648860, 2025). "Abnormal accumulations of TAR DNA-binding protein 43kDa (TDP-43) are present in the neurons and glia of patients with amyotrophic lateral sclerosis (ALS) and various forms of frontotemporal lobar degeneration (FTLD)." (PMID 40933733, 2025). "Other groups of FTLD, alongside most cases of amyotrophic lateral sclerosis (ALS) instead show accumulation of TAR DNA binding protein-43 (TDP-43)." (PMID 39161653, 2024). "Amyotrophic lateral sclerosis (ALS) is a progressive motor neuron disease characterised by the deposition of aggregated proteins including TAR DNA-binding protein 43 (TDP-43) in vulnerable motor neurons and the brain." (PMID 38252383, 2024). "TAR DNA-binding protein 43 (TDP-43) plays a crucial role in several neurodegenerative diseases, including amyotrophic lateral sclerosis (ALS) and frontotemporal dementia (FTD)." (PMID 39728746, 2024). "Tau aggregates condensation via LLPS is similar to amyotrophic lateral sclerosis (ALS)-associated protein aggregates of Fused in Sarcoma (FUS), hnRNPA1, and TAR DNA-binding protein 43 (TDP43)." (PMID 39596399, 2024). "Approximately 40–55% of amyotrophic lateral sclerosis (ALS) cases are attributed to mutations in over 50 identified ALS-associated genes; among these, pathogenic mutations in SOD1, C9ORF72, FUS, and TARDBP are the most prevalent." (PMID 38927671, 2024). "For example, TAR DNA binding protein of 43 kDa (TDP‐43) is involved in apoptosis, cell division, and axonal transport through regulation of transcription, alternative splicing, and mRNA stability in frontotemporal dementia, AD, and amyotrophic lateral sclerosis." (PMID 38376022, 2024). "Inclusions containing TAR DNA binding protein 43 (TDP-43) are a pathological hallmark of frontotemporal dementia (FTD) and amyotrophic lateral sclerosis (ALS)." (PMID 38635657, 2024). "The TAR-DNA binding protein (TDP43) is a nuclear protein whose cytoplasmic inclusions are hallmarks of Amyotrophic Lateral Sclerosis (ALS)." (PMID 37450246, 2023).
amyotrophic lateral sclerosis (continued). "Loss of nuclear TDP-43 occurs in a wide range of neurodegenerative diseases, and specific mutations in the TARDBP gene that encodes the protein are linked to familial Frontal Temporal Lobar Dementia (FTD), and Amyotrophic Lateral Sclerosis (ALS)." (PMID 38168388, 2023). "TAR DNA-binding protein of ~ 43 kDa (TDP-43) proteinopathies represent a clinicopathologic spectrum anchored clinically on either end by amyotrophic lateral sclerosis (ALS) and frontotemporal degeneration (FTD)." (PMID 38062485, 2023). "IDPs associated with common neurodegenerative diseases include amyloid beta (Aβ) and tau for Alzheimer’s disease (AD), α-synuclein (α-syn) for Parkinson’s disease (PD), and TAR DNA-binding protein (TDP-43) for amyotrophic lateral sclerosis (ALS)." (PMID 36834792, 2023). "Depletion or mutations in genes encoding RBPs like TDP-43 (TAR DNA-binding protein 43), FUS (fused in sarcoma), and FMRP (fragile X mental retardation protein) leads to human neurological disorders such as spinal muscular atrophy, amyotrophic lateral sclerosis, and fragile X syndrome." (PMID 36758804, 2023). "TAR DNA binding protein 43 (TDP-43) pathology is a key feature of over 95% of amyotrophic lateral sclerosis (ALS) and nearly half of frontotemporal dementia (FTD) cases." (PMID 37012334, 2023). "TAR DNA-binding protein 43 (TDP-43) is a predominant component of inclusions in the brains and spines of patients with amyotrophic lateral sclerosis (ALS)." (PMID 35954242, 2022). "Indeed, we could find TAR DNA-binding protein 43 (TDP43), which is the main component of protein aggregates in amyotrophic lateral sclerosis, to be higher abundant in NMGs than in SNSurr. tissue." (PMID 35852604, 2022). "Amyotrophic lateral sclerosis (ALS) is a fatal neurodegenerative disease with no cure or effective treatment in which TAR DNA Binding Protein of 43 kDa (TDP-43) abnormally accumulates into misfolded protein aggregates in affected neurons." (PMID 35581326, 2022). "For example, TAR DNA-binding protein 43 (TDP-43) forms amyloid aggregates in the neurons of patients with amyotrophic lateral sclerosis (ALS)." (PMID 33244624, 2021). "Interestingly, this BRCA1 colocalization was not seen with alpha-synuclein or TARDBP (TAR DNA-binding protein) inclusions, histopathological features associated with Parkinson’s disease and amyotrophic lateral sclerosis, respectively." (PMID 34222870, 2021). "Mutations in RNA-binding proteins (RBPs) such as TAR DNA-binding protein 43 (TDP-43) and fused in sarcoma (FUS) are associated with amyotrophic lateral sclerosis (ALS) and frontotemporal dementia (FTD)." (PMID 32184412, 2020). "Amyotrophic lateral sclerosis (ALS) and frontotemporal lobar degeneration (FTLD), 2 incurable neurodegenerative disorders, share the same pathological hallmark named TDP43 (TAR DNA binding protein 43) proteinopathy." (PMID 33021970, 2020). "Abnormal accumulation of TAR DNA-binding protein 43 (TDP-43), a DNA/RNA binding protein, is a pathological signature of amyotrophic lateral sclerosis (ALS)." (PMID 31959210, 2020). "These diseases most commonly comprise Alzheimer’s disease (AD), characterized by the proteins amyloid-β and tau, Parkinson’s disease (PD; α-synuclein), and amyotrophic lateral sclerosis (ALS), in which TAR DNA-binding protein 43 deposition is observed." (PMID 32580348, 2020). "Mutations in progranulin cause frontotemporal lobar degeneration (FTLD), and progranulin exerts neuroprotective roles against TAR DNA-binding protein 43 aggregation, the latter a feature of amyotrophic lateral sclerosis (ALS) and FTLD." (PMID 32435656, 2020). "These include amyloid-beta peptide (Aβ) and hyperphosphorylated tau protein in AD, Lewy body containing α-synuclein in PD, mutant huntingtin (Htt) in HD, TAR DNA-binding protein-43 (TDP-43) in amyotrophic lateral sclerosis (ALS), and others." (PMID 31324048, 2019).